NLRP3 (NLR family pyrin domain containing 3)
Diseases named in the same sentence as NLRP3 in open-access papers (continued):
Sharing a sentence is not in itself a finding about the gene and the disease.
endometriosis (34 papers, 2018 to 2026). The growth of functional endometrial tissue in anatomic sites outside the uterine body. "Treating mice with MCC950, a small-molecule NLRP3-specific inhibitor, reduced endometriosis lesion size, suggesting a pathogenic role of NLRP3 hyperactivation in endometriosis." (PMID 40794443, 2025). "Elevated NLRP3 expression in defective macrophages and endometrial stromal cells is associated with endometriosis." (PMID 39769450, 2024). "Further, NLRP3 activation has been associated with endometriosis, where defective macrophages and endometrial stromal cells elevate the expression of NLPR3." (PMID 39769450, 2024). "The remarkably elevated mRNA expression of the NLRP3 inflammasome suggests a close association between endometriosis pathogenesis and inflammation." (PMID 38313171, 2023). "Here, we demonstrated that endometriosis in rats caused the activation of NLRP3 and NF-κB pathways as well as the increase in levels of IL-1β and TNF-α, while fisetin inhibited the activation of NLRP3/NF-κB as well as diminished the levels of IL-1β and TNF-α." (PMID 36982152, 2023). "The aberrant activation of inflammasomes, especially the NLRP3 inflammasome, is closely linked to the development of endometriosis." (PMID 38313171, 2023). "Chang used expression profiling to identify mechanisms involved in the malignant transformation of endometriosis to ovarian cancer; 18 genes were identified, including NLRP3, IL-1B, and IL-18, which implicated inflammasomes." (PMID 31923221, 2020). "TRIM24, through NLRP3 ubiquitination and pyroptosis, causes endometriosis." (PMID 39769450, 2024). "This study investigates the role of the TLR4/NF-κB/NLRP3 inflammasome axis in endometriosis pathogenesis and evaluates the therapeutic potential of pharmacologic TLR4 inhibition." (PMID 42123727, 2026). "Granulosa cells from women with endometriosis show elevated levels of the NLRP3 inflammasome and increased IL-1β and IL-18 in follicular fluid, contributing to infertility." (PMID 40508002, 2025). "Interactions between macrophages and endometrial stromal cells via NLRP3 signaling enhance stromal cell migration and endometriosis progression." (PMID 40508002, 2025). "Estrogen activates NLRP3 through the estrogen response element, linking it to endometriosis pathology." (PMID 39769450, 2024). "have shown that NLRP3 inflammasome activation through IncRNA NEAT/miR-141-3p/HTRA1 pathway leads to endometriosis." (PMID 39769450, 2024). "Alpha-lipoic acid has been shown to prevent endometriosis by preventing the NLRP3-mediated release of IL-1β and IL-18." (PMID 39769450, 2024). "The significance of NLRP3 inflammasome in endometriosis is further confirmed by studies using various antioxidants and NLRP3 inhibitors." (PMID 39769450, 2024). "NLRP3 inflammasome activation through IncRNA NEAT/miR-141-3p/HTRA1 pathway contributes to endometriosis." (PMID 39769450, 2024). "Abnormal activation of the NLRP3 inflammasome has been observed within ectopic endometrial lesions, peritoneal fluid, and the eutopic endometrium of women with endometriosis." (PMID 39061077, 2024). "Antioxidants like fisetin, MCC950, and alpha-lipoic acid inhibit NLRP3-mediated inflammation and prevent endometriosis." (PMID 39769450, 2024). "Estrogen has been shown to activate NLRP3 inflammasome through the estrogen response element, and is involved in the pathology of endometriosis." (PMID 39769450, 2024). "NLRP3 is also upregulated in endometriosis, and inhibiting NLRP3 levels can reduce IL-1β levels in stromal cells." (PMID 39595579, 2024). "NLRP3 inflammasome-mediated activation of pyroptosis can affect angiogenesis in endometriosis in a Notch1-dependent manner." (PMID 38397379, 2024). "NLRP3/IL-1β contributed to the etiology of endometriosis, and NLRP3 suppressors (MCC950) possibly helped to reduce ovarian endometriosis as well as enhanced the functionality of ovaries affected by endometriosis." (PMID 37033937, 2023).
endometriosis (continued). "This study aimed to assess messenger ribonucleic acid (mRNA) NLRP3 inflammasome levels in women experiencing infertility due to endometriosis who are undergoing assisted reproductive technologies with the addition of probiotics." (PMID 38313171, 2023). "Targeted suppression of NLRP3 dramatically slowed the progression of endometriosis lesions and fibrogenesis in a mouse model of endometriosis." (PMID 37033937, 2023). "In contrast, in the endometriosis group, statistically significant changes in NLRP3 levels were observed before and after treatment (p<0.001, Wilcoxon test)." (PMID 38313171, 2023). "Further studies report that MC activation by estrogen plays a crucial role in the development of endometriosis, through NLRP3 inflammasome activation." (PMID 36982152, 2023). "Targeted inhibition of NLRP3 considerably restrained lesion development and fibrogenesis in a mouse model of endometriosis." (PMID 36982152, 2023). "Investigations have revealed that reducing NLRP3 levels inhibits the production of inflammatory cytokines, indicating the potentially significant role of the NLRP3 inflammasome in endometriosis pathogenesis." (PMID 38313171, 2023). "Statistically significant differences were observed when comparing NLRP3 levels before treatment between the control and endometriosis groups (p<0.001, Mann-Whitney U-test)." (PMID 38313171, 2023). "In contrast, within the endometriosis group, NLRP3 levels varied, with the majority falling into the low category." (PMID 38313171, 2023). "Statistically significant differences in NLRP3 levels after treatment were identified when comparing the control and endometriosis groups (p=0.003) using Pearson's chi-square test." (PMID 38313171, 2023). "It has been suggested that NLRP3 inflammasome, which leads to the activation of IL-1β, contributes to the progression of endometriosis." (PMID 36982152, 2023). "According to their research, mast cells were involved in the development of endometriosis through the activation of the NLRP3 inflammasome, which is known to be a nuclear-initiated estrogen signaling pathway." (PMID 37033937, 2023). "The latest study also demonstrated the role of NLRP3/caspase-1/IL-1β-mediated pyroptotic pathway in endometriosis." (PMID 36354688, 2022). "Altogether, our data demonstrated a distinct alleviating role of NLRP3 inhibitor in the pathogenesis and fibrosis of endometriosis." (PMID 34630429, 2021). "Taken together, our study provided mechanistic evidence of how estrogen can promote MC-derived NLRP3 inflammasome activation and IL-1β secretion, which lead to the development of endometriosis." (PMID 34630429, 2021). "Collectively, these findings suggest that MCs contribute to the development of endometriosis through NLRP3 inflammasome activation mediated by nuclear-initiated estrogen signaling pathway." (PMID 34630429, 2021). "Merged images show the co-localization of NLRP3 (shown as red) and the mast cell marker, tryptase (shown as green), indicating that NLRP3 was expressed in MCs in endometriosis." (PMID 34630429, 2021). "To investigate the role of MC-derived NLRP3 inflammasome in endometriosis, we intraperitoneally injected the NLRP3 inhibitor CY-09 into the established endometriosis mouse model." (PMID 34630429, 2021). "Accordingly, IL-1β levels in the peritoneal fluid of mice with endometriosis were elevated compared with the sham group and were reduced when exposed to the NLRP3 inhibitor." (PMID 34630429, 2021). "Targeted inhibition of NLRP3 significantly restrained lesion progression and fibrogenesis in a mouse model of endometriosis." (PMID 34630429, 2021). "It was reported that the NLRP3 inflammasome was involved in the exacerbation of endometriosis in a mouse model, consistent with our current findings showing smaller lesions in IL-1R1-deficient mice." (PMID 31507610, 2019).
endometriosis (continued). "The TLR4/NF-κB/NLRP3 axis may drive endometriosis progression by linking innate immunity, inflammasome activation, pyroptosis, with possible involvement in angiogenesis warranting further investigation." (PMID 42123727, 2026). "Fisetin, a polyphenol, may reduce endometriosis by modulating the nucleotide-binding domain, leucine-rich-repeat-containing family, pyrin domain-containing-3 (NLRP-3) inflammasome pathway and reducing oxidative stress in mast cells." (PMID 40004777, 2025). "TRIM24 potentially facilitates endometriosis progression through the NLRP3/caspase-1/IL-1β pathway." (PMID 40508002, 2025). "Aberrant NLRP3 activation has been closely associated with a wide range of human disorders, including cardiovascular disease, neurodegeneration, metabolic dysfunction–associated steatohepatitis (MASH), non–small cell lung cancer (NSCLC), and endometriosis." (PMID 40794443, 2025). "Overactive estrogen receptors diminish HDL function and elevate TG and NHHR, which then activate the NLRP3 inflammasome and drive excessive IL-1β release, sustaining lesion growth and underscoring the pivotal role of the lipid–inflammation axis in endometriosis." (PMID 41268163, 2025). "NLRP3-mediated pyroptosis is associated with fibrosis via TGF-β1, and inhibiting it may reduce fibrosis in endometriosis." (PMID 40508002, 2025). "Research suggests that the NLRP3 inflammasome could be involved in the development of endometriosis." (PMID 38177104, 2024). "NLRP3, IL-1β, and IL-18 are upregulated during transformation of endometriosis to ovarian cancer." (PMID 39769450, 2024). "Similarly, elevated NLR family pyrin domain-containing 3 (NALP3) inflammasome levels have been observed in the ovaries of endometriosis patients." (PMID 40226698, 2024). "The NLRP3/IL-1β pathway plays a role in endometriosis development, and NLRP3 inhibitors may help reduce ovarian endometrioma size and improve ovarian function." (PMID 40034240, 2024). "Previous studies have suggested that the development of endometriosis may be influenced by the NLRP3 inflammasome." (PMID 37033937, 2023). "Therefore, this study aimed to explore the antioxidant effect of fisetin on endometriosis considering the contribution of mast cells and the NLRP3 inflammasome pathway." (PMID 36982152, 2023). "NLRP3 levels were assessed before and after treatment in the control and endometriosis groups." (PMID 38313171, 2023). "In conclusion, fisetin could represent a new therapeutic strategy to control endometriosis perhaps by targeting the MC-derived NOD-like receptor family pyrin domain containing 3 (NLRP3) inflammasome pathway and oxidative stress." (PMID 36982152, 2023). "In this study, we provided mechanistic data on how fisetin, a natural flavonol, could have a positive action on estrogen-dependent endometriosis modulating MC-derived NLRP3 inflammasome." (PMID 36982152, 2023). "Interestingly, a recent study showed that activation of MCs by NLRP3 contributed to the development of endometriosis." (PMID 35720309, 2022). "To identify whether NLRP3 is involved in endometriosis, we detected the expression of NLRP3 in e/nEM and OE using qRT-PCR and western blot analysis." (PMID 35351143, 2022). "Previous studies have reported that the NLRP3 inflammasome may be related to the progression of endometriosis." (PMID 35351143, 2022). "Interestingly, NLRP3−/− mice exhibit smaller ectopic lesions compared to wild type mice, thus suggesting that NLRP3 induces endometriosis." (PMID 33716981, 2021). "Our in vivo data supported that NLRP3 inhibitor CY-09 could suppress IL-1β production in MCs and protect against lesion development and fibrosis in endometriosis." (PMID 34630429, 2021). "We further characterized the impact of NLRP3 inhibitor in the pathogenesis of endometriosis." (PMID 34630429, 2021).
endometriosis (continued). "Our results indicate that the exposure of MCs to estrogen stably drives NLRP3 expression critical for caspase-1 activation and IL-1β secretion, which might contribute to the local proinflammatory environment in endometriosis." (PMID 34630429, 2021). "Compellingly, the local high estrogen environment of endometriosis may lead to the changes of NLRP3 inflammasome in MCs, and its specific role in the development of the disease was worthy of our exploration." (PMID 34630429, 2021). "Notably, recent concepts depicting the therapeutic role of IL-1β in endometriosis have emerged, raising the question of which one is the better treatment strategy, targeting IL-1β or NLRP3, or even a combined regimen." (PMID 34630429, 2021). "Thus, we revealed that butyrate may have beneficial effects against endometriosis by inhibiting the activation of NLRP3 inflammasome." (PMID 38505548, 2024). "Indeed, the NLRP3 inflammasome induces caspase-1 and IL-1β in endometriosis." (PMID 36093086, 2022). "Moreover, transient inhibition or reduction of miR-223 expression exacerbated endometriosis, as indicated by the histological indices, increased NLRP3, IL-1β, IL-6, and TNF-α secretion, as well as the IL-1β-inducible chemokines CXCL1 and CXCL2 mRNA transcripts." (PMID 30186287, 2018). "NLR family pyrin domain containing 3 (NLRP3) and NLR family CARD domain containing 5(NLRC5) have prominent improving effects on endometriosis with altering fibrosis and inflammation in previous studies." (PMID 40034240, 2024). "Treatment with fisetin notably inhibited the NLRP3, ASC, and cleaved caspase-1 expression in endometriotic tissues of vehicle rats subjected to endometriosis." (PMID 36982152, 2023). "Although to date, substantial evidence does not exist, the NLRP3 inflammasome has been indirectly related to the pathophysiology of endometriosis in several review articles." (PMID 36381820, 2022). "We hypothesized that inhibiting NLRP3 with MCC950 would suppress interleukin-1 beta (IL-1β) and alleviate endometriosis." (PMID 35351143, 2022). "In this study, we first examined the expression of NLRP3 in the eutopic endometrium (EM) with and without endometriosis and OE samples." (PMID 35351143, 2022). "Additionally, our results suggest that the EM is similar with and without endometriosis, and that NLRP3 is elevated due to inflammation during the OE process and due to the contents of the OE itself." (PMID 35351143, 2022). "Tranilast, an NLRP3 inhibitor that is clinically applied as an anti-allergic drug but is less specific than MCC950, is of interest to us because it may have a positive impact on the treatment of endometriosis." (PMID 35351143, 2022). "The NLRP3 level was significantly higher than that of other NLRs in OE samples and CSCs; therefore, the specific inhibition of NLRP3 by MCC950 could suppress IL-1β production in endometriosis, while essential responses against bacterial infections may remain intact." (PMID 35351143, 2022).
lymphoma (34 papers, 2012 to 2024). A malignant (clonal) proliferation of B- lymphocytes or T- lymphocytes which involves the lymph nodes, bone marrow and/or extranodal sites. "We can, therefore, only assume that these genetic aberrations predispose lymphoma cells to the initiation and perpetuation of NLRP3 inflammasome signaling via either structural differences or the quantitative increase in its related protein components." (PMID 38397043, 2024). "Nevertheless, drugs predominantly tested for their potential to inhibit other pathways implicated in lymphoma development were shown to exert part of their action via interference with the NLRP3 inflammasome pathway." (PMID 38397043, 2024). "Studies determined NLRP3 inflammasome upregulation in SjS patients and increased susceptibility to the development of lymphoma." (PMID 35897704, 2022). "Some other studies more broadly have implicated the NLRP3 inflammasome in cancer and links to proliferation of T cells/lymphoma cells." (PMID 31379813, 2019). "In hematological diseases, genetic polymorphisms of the NLRP3 have been reported to contribute to the pathogenesis of multiple myeloma and lymphoma." (PMID 31428046, 2019). "In this study, we investigated the polymorphism and expression of NLRP3 inflammasome related genes in lymphoma patients and evaluated their clinical relevance." (PMID 29312552, 2017). "Because of the aberrant polymorphism and expression of NLRP3 inflammasome in lymphoma, we further used lymphoma cell line Pfeiffer to explore their function and mechanism." (PMID 29312552, 2017). "Here, we investigated the polymorphism and expression of NLRP3 inflammasome related genes and explored their function in lymphoma." (PMID 29312552, 2017). "In conclusion, NLRP3 inflammasome contributes to the susceptibility and plays a carcinogenic role through its effector cytokine IL-18 in lymphoma." (PMID 29312552, 2017). "Similarly, NLRP3-associated IL-18 is found in high levels in plasma of lymphoma and multiple myeloma patients where IL-18 is a predictor of poor survival in multiple myeloma patients, esophageal carcinoma, renal cell carcinoma and gastric carcinoma." (PMID 37298187, 2023). "Moreover, specific gene variants of the NLRP3 inflammasome were correlated with a susceptibility to developing lymphomas, ALL, CML, and possibly MM." (PMID 35897704, 2022). "NLRP3 inflammasome activation seems to exert a dual role, pro- and antitumorigenic, depending on the type of lymphoma." (PMID 38397043, 2024). "Exploiting the role of the NLRP3 inflammasome in the pathogenesis of lymphoma is an attractive field for the development of new treatment strategies, though research results are still immature." (PMID 38397043, 2024). "Considering this observation, it can be proposed that IL-18, secreted as a result of NLRP3 inflammasome activation in the setting of lymphoma, can induce signaling pathways promoting lymphomagenesis via its interaction with the IL-18R on lymphoma B-cells." (PMID 38397043, 2024). "It has been shown that the NLRP3 inflammasome regulates PD-L1 and immune cells to promote immunosuppression, while IL-18 negatively impacts anti-lymphoma immunity in vivo." (PMID 38177104, 2024). "For most lymphoma subtypes, NLRP3 inflammasome activation was shown to act as a tumor-promoting factor, but a tumor-suppressive role was also described." (PMID 38397043, 2024). "Aberrations of the NLRP3 inflammasome pathway not only affect lymphoma cell growth and proliferation but also modulate the TME." (PMID 38397043, 2024). "IFN-α based immunotherapies were used for the treatment of lymphomas both of B- and T-cell origin, possibly exerting a part of their therapeutic effect via mitigating the degree NLRP3 inflammasome activation." (PMID 38397043, 2024). "In the following section, we review the effects of NLRP3 inflammasome activation on lymphoma cells and on immune cells of the TME." (PMID 38397043, 2024).